FMR1 (fragile X messenger ribonucleoprotein 1)
Diseases named in the same sentence as FMR1 in open-access papers (continued):
Sharing a sentence is not in itself a finding about the gene and the disease.
cancer (49 papers, 2012 to 2026). A tumor composed of atypical neoplastic, often pleomorphic cells that invade other tissues. "The relevance of the current report extends beyond systemic metabolic pathways as both Fmr1 and Tgr5 are implicated in cancer pathobiology." (PMID 41525319, 2026). "This interest arises mainly because of the implications of DNA methylation in cancer development, as well as neuropsychiatric diseases such as Fragile X syndrome, where hyper-methylation at the Fragile X Mental Retardation-1 (FMR-1) gene is associated with intellectual disability." (PMID 29723958, 2018). "As the table further demonstrates, the non-cancer patient populations in the U.S. (controls for the Austrian study) and Italy demonstrated a relative low prevalence of low FMR1 alleles in the 20.5–23.1% range, while Israeli controls were reported to demonstrate as much a 31.5% low FMR1 alleles." (PMID 25036526, 2014). "We performed pan-cancer expression analysis of FMR1 using the TIMER2.0 platform, and evaluated its differential expression in gastric cancer versus normal gastric tissues in the TCGA cohort." (PMID 41184982, 2025). "One example of an FMR1-targeting microRNA is miR-323a-3p, which performs a tumor-suppressor function in various cancers by targeting FMR1 and suppressing its levels." (PMID 40244008, 2025). "FMR1 is an interesting RBP, since it is associated with cancer cell growth, metastasis, EMT, apoptosis, and angiogenesis, and has 35 binding sites in circHIPK3." (PMID 40061896, 2025). "Our pan-cancer analysis further revealed that FMR1 exhibits differential expression patterns across cancer types." (PMID 41184982, 2025). "Despite its well-established role in the brain, in cancer cells FMR1 binds mRNAs involved in EMT and regulates their stability and translation." (PMID 37298909, 2023). "A more recent study showed that systemic injection of a novel p110β-specific inhibitor GSK2702926A, a similarly structured compound of which is under investigation in a cancer clinical trial, rescues cellular and behavioral abnormalities in Fmr1 KO mice." (PMID 32179850, 2020). "Amongst 80 cancer patients for whom FMR1 data were available, only 27 (33.8%) were BRCA-positive, 21 carriers of BRCA1 and 6 of BRCA2 mutations." (PMID 25036526, 2014). "Mice orthotopically injected with Fmr1 silenced cells have less circulating cancer cells compared to control as detected by GFP mRNA levels." (PMID 24092663, 2013). "Women with low FMR1 sub-genotypes, therefore, should reflect increased BRCA1/2-associated cancer risks, while the remaining approximately 75 percent should face almost no such risks." (PMID 22984553, 2012). "Currently, FMR1 is known to be involved in regulating cancer progression as a novel m6A reader." (PMID 40118855, 2025). "circHIPK3 contains multiple sites for the same RBPs (e.g., DDX54, EIF4A3, FMR1, IGF2BP1, IGF2BP2, LIN28B and MOV10), many of which are involved in chemoresistance and organelle-like structures, such as Cajal body and P-body which are associated with cancer." (PMID 40061896, 2025). "The new m6A reader FMR1 is also involved in the regulation of cancer progression." (PMID 39062595, 2024). "In CRC, FMR1 can recognize m6A modification sites in the mRNA of key molecules involved in cancer occurrence and targeted therapy, such as epidermal growth factor receptor, and maintain their stability and expression in an m6A-dependent manner, thereby promoting tumorigenesis and metastasis of CRC." (PMID 39062595, 2024). "FMR1, a new m6A reader, is known to be involved in the regulation of cancer progression." (PMID 36347844, 2022).
cancer (continued). "There are 10 highly significant, direct and physical associators with a confidence score of ≥5.0 namely – RELA, HMOX2, EZH2, p-10Y-ERBB3-1, WDR1, ERRFI1, PRG2, FMR1, DEFA6-(?-100), cytf_human and the majority of the network associators of POTEE are epigenetically activated in many cancers." (PMID 34788504, 2021). "Links between FMR1 and other cancer types have been recently reported." (PMID 32260317, 2020). "As a clinical screening tool, genetic testing (beyond karyotype and FMR1 testing via WES/NGS) may help to associate a diagnosis of POI with a specific syndrome, cancer predisposition, or neurodegeneration." (PMID 32934798, 2020). "With FMR1 apparently at crossroads of reproduction, immunology and cancer, it is tempting to hypothesize about such, each other opposing, functions for the two het sub-genotypes of FMR1, het-norm/high and het-norm/low." (PMID 22984553, 2012). "Therefore, FMR1 may affect the EMT process through regulating the m6A modification of its downstream molecules in cancer, and the regulation of FMR1 on the M6A modification of EMT-related molecules deserves further investigation." (PMID 40118855, 2025). "Additionally, FMR1 mRNA expression was positively correlated with HPV-associated HNSC and metastatic skin cutaneous melanoma (SKCM) (P < 0.001), indicating that FMR1 may play an important role in the tumorigenesis and progression of diverse cancers." (PMID 41184982, 2025). "Moreover, the overexpression of FMR1 may promote the proliferation and survival of cancer cells by regulating the cell cycle, DNA repair, and anti—apoptotic pathways." (PMID 41184982, 2025). "Members of the fragile X protein (FXP) family (FMR1, FXR1 and FXR2) are differentially expressed in most types of cancer and major neurodegenerative diseases." (PMID 41117937, 2025). "We found that KLF3 expression was generally positively correlated with m1A, m5C, and m6A-related gene expression in pan-cancer, especially in YTHDF1, NSUN3, TET2, METTL14, YTHDC2, and FMR1." (PMID 37600783, 2023). "In line with findings from the database, the expression of FMR1 mRNA and protein in CRC tissues were a strong overexpression in a subset of patients compared with paired normal intestinal mucosa adjacent to cancer." (PMID 36347844, 2022). "Our study shows that the tandem Tudor in FXR1 binds to methylated lysine in histone H3 in a similar manner as that in FMR1 and it is required for FXR1’s function in regulating cancer cell proliferation." (PMID 28767039, 2017). "In addition, m6A‐recruited the binding proteins, YTHDC1, YTHDC2, YTHDF3, and FMR1 were inversely correlated, while HNRNPC, HNRNPA2B1, YTHDF1, and RBMX positively correlated TSs in most cancer types." (PMID 36239411, 2023). "Mechanically, FMR1 recognized the m6A-modification site in EGFR mRNA, a key molecule in cancer occurrence and targeted therapy, sustained its stability and maintained its expression in an m6A-dependent manner, thereby promoting the tumorigenesis and metastasis of CRC." (PMID 36347844, 2022). "As expected the level of FXR1 is highly amplified in cancer tissues compared to normal adjacent tissues and we do not see differential expression of FMR1 and FXR2." (PMID 27606879, 2016).
tumor (46 papers, 2012 to 2026). "Our results verified that FMR1 expression was significantly reduced in ccRCC and that decreased FMR1 expression was closely associated with higher tumor stages (T3/T4), distant metastasis (M1), and shorter OS." (PMID 40118855, 2025). "The differential expression of FMR1 in gastric cancer was strongly associated with the activity of multiple immune cell types within the tumor microenvironment." (PMID 41184982, 2025). "In the current study, we validated the low-expression status of FMR1 in ccRCC, and its decreased expression was closely associated with higher tumor stages, metastasis, and poor prognosis of patients." (PMID 40118855, 2025). "MiR-323a-3p was significantly associated with survival and acted as a tumor suppressor by inhibiting proliferation, migration, and invasion via the regulation of FMR1." (PMID 35351128, 2022). "Confirming such a growth arrest-reversing function of low FMR1 alleles would, of course, have major relevance for the current understanding of tumor induction and diagnostic tumor risk assessments." (PMID 22984553, 2012). "FMR1 has recently been implicated in post-transcriptional control of immune checkpoint genes and RNA transport, providing a novel link between RNA modification and tumor immunity." (PMID 40565233, 2025). "Besides, we also detected a low-expression state of FMR1 in ccRCC using TCGA-KIRC data, and lower expression of FMR1 was closely associated with higher tumor stages and grades (T3/T4, G3/G4 and Stage III/IV)." (PMID 40118855, 2025). "Differential expression analysis and ceRNA network analysis showed several tumor-associated transcripts (Dock4, Fmr1, Zfhx3, Ralb, Mll, Aoc3, and circHRH4) may involve in ALV-J-induced tumorigenesis." (PMID 30286182, 2018). "Preclinical studies on using the FMR1 gene as a target to guide tumor treatment have currently achieved some preliminary results." (PMID 41184982, 2025). "Loss of FMR1 hinders m6A‐dependent decay of ADAM17 mRNA, resulting in ADAM17 accumulation in tumor exosomes and enhanced angiogenesis." (PMID 41058008, 2025). "The resulting loss of FMR1 disrupts m6A‐dependent recognition and decay of ADAM17 mRNA, leading to ADAM17 accumulation and enhanced tumor angiogenesis." (PMID 41058008, 2025). "FMR1 expression was significantly higher in patients with advanced pathological tumor stages, particularly in the pT3 and pT4 combined stages and the pN1 nodal stage." (PMID 39000397, 2024). "Our results show that most of the genes are negatively correlated with these drugs (based on IC50 values) between high- and low-risk groups in each tumor except for RBFOX2 in some tumors, YTHDF1 in SKCM and LUAD, FTO in LUSC and TGCT, and FMR1 in OV and UCS." (PMID 39457524, 2024). "Tumour tissues in the high circRBM33-expression group tended to have higher FMR1 scores than those in the low circRBM33-expression group." (PMID 37056926, 2023). "Taken together, we assume that circRBM33 interacts with FMR1 to form a complex that exerts its tumour-promoting effects in PCa." (PMID 37056926, 2023). "To reproduce tumor growth and mimic the clinical pattern of tumor behavior, we used a xenograft mouse model, demonstrating in vivo that the silencing of FMR1 gene affects GSC growth capability." (PMID 35982038, 2022). "The numbers of tumor nodules in liver metastasis increased significantly when FMR1 was overexpressed as compared with the control group." (PMID 36347844, 2022). "FXR1 mRNA is overexpressed in tumor compared to normal adjacent tissues, whereas FMR1 and FXR2 mRNA levels are comparable to their normal mRNA expression." (PMID 27606879, 2016). "In two other independent cohorts, i.e., EMC-344 and MSK-99, we found significantly increased FMR1 mRNA expression in primary tumours that metastasize to lung." (PMID 24092663, 2013). "Analysis of the TRANSBIG cohort revealed trend of increasing expression of FMR1 mRNA in primary tumours that metastasize to distal organs." (PMID 24092663, 2013).
tumor (continued). "In this study, we analyzed FMR1 expression in gastric cancer tissues and normal gastric mucosal tissue, examined its relationship with clinicopathological features and patient prognosis, and explored its role in tumor immune microenvironment modulation." (PMID 41184982, 2025). "FMR1 was selectively upregulated in tumor-derived epithelial cells, suggesting that it may play a key regulatory role in the occurrence and development of gastric cancer." (PMID 41184982, 2025). "Moreover, the functions of FMR1 vary across tumor stages and anatomical sites, consistent with its heterogeneous expression in different human tissues." (PMID 41184982, 2025). "Together, these findings suggest that FMR1 may influence tumor progression through multiple downstream effectors; however, we focused on the c-MYC pathway as the downstream regulatory axis of greatest interest for further investigation." (PMID 41184982, 2025). "Recent research has deepened our understanding of FMR1′s role in cancer biology, highlighting its involvement in key metabolic pathways that support cancer cell survival, proliferation, and immune modulation within the tumor microenvironment (TME)." (PMID 40563420, 2025). "Likewise, IHC demonstrated that tumour tissues had higher FMR1 levels than normal tissues, and the worse the malignance was, the more FMR1 was expressed." (PMID 37056926, 2023). "In light of both circRBM33 and FMR1 acting as pro-tumor factors, we tested whether they affect each other at the transcriptional or translational level." (PMID 37056926, 2023). "Moreover, the tumor weight and percentage of Ki67-positive cells in subcutaneous tumors of FMR1 overexpression was higher." (PMID 36347844, 2022). "In our study, FMR1 was correlated with several types of tumor-infiltrating immune cells, suggesting that FMR1 may be involved in the regulation of immune cells in the tumor microenvironment." (PMID 36189296, 2022). "Furthermore, FMR1 shRNA plasmid carried by attenuated Salmonella has an effective anti-tumor effect in vivo." (PMID 36347844, 2022). "Furthermore, we determined the tumor suppressive function of miR-323a-3p was achieved by targeting the fragile X mental retardation 1 (FMR1) gene to inhibit proliferation, migration, and invasion, both in vitro and in vivo." (PMID 35351128, 2022). "Further analysis showed that miR-323a-3p mediated tumor-related functions by targeting FMR1." (PMID 35351128, 2022). "The results showed that tumor volumes and weights were significantly increased when FMR1 was overexpressed, though this phenomenon could be reversed by EGFR knockdown." (PMID 36347844, 2022). "However, after adjusted to age, molecular classification, grade, tumor size, lymph node status, endocrine treated, and chemotherapy treated, only YTHDC1, FMR1, IGF2BP1 and WTAP showed a significant association." (PMID 34141492, 2021). "FXR1 and FMR1 mRNAs are significantly (p<0.0001) expressed in tumor samples compared to normal." (PMID 27606879, 2016). "Tumours also showed higher levels of Fmrp and Fmr1 mRNA compared to healthy breast tissues." (PMID 24092663, 2013). "These two groups of immune cells exert opposing functions within the tumor immune microenvironment, and the consistency of our findings suggests that FMR1 may be involved in shaping the immune infiltration landscape of gastric cancer, thereby influencing immune balance and tumor progression." (PMID 41184982, 2025). "In-depth investigation of the regulatory mechanisms of FMR1 in tumor biology is crucial for the clinical implementation of targeted therapeutic strategies against FMR1.However, the expression and functional significance of FMR1 in gastric cancer remain largely unknown." (PMID 41184982, 2025). "More importantly, the protein expression level of FMR1 was positively correlated with the expression level of circRBM33 in our tissue microarrays, which further suggested that the circRBM33-FMR1 binary complex might coactivate tumour progression in PCa." (PMID 37056926, 2023).
tumor (continued). "Meanwhile, the authors also observed the moderate reduction of Tregs number in Fmr1−/‐ Ccl7−/− group, but no change in the expression of tumor‐associated macrophages (TAMs) markers involved in immunosuppression, indicating that CCL7 was only involved in the regulation of inflammation by T cells." (PMID 36968189, 2023). "Guided by bioinformatic predictions, we therefore co-cultured tumor cells with CD4+ T cells and measured cytokines in the supernatant, and the results confirmed that FMR1 promotes CD4+ T-cell activation." (PMID 41184982, 2025). "After further screening, we evaluated the relationship between expression of FMR1, LRPPRC, RBMX, YTHDC2, IGF2BP1 and clinical parameters, including stage, T (tumor infiltrating), N (lymphatic metastasis) and M (distant metastasis) in CRC." (PMID 37194014, 2023). "The results showed conspicuously higher RBMX, FMR1 and IGF2BP1 expression in tumor tissues, especially RBMX." (PMID 37194014, 2023). "We evaluated the relationship between expression patterns of RBMX, FMR1, LRPPRC, YTHDC2, IGF2BP1 and clinical parameters, including stage, T (tumor infiltration), N (lymphatic metastasis), M (distant metastasis) in CRC." (PMID 37194014, 2023). "To further investigate the mechanisms by which miR-323a-3p acted as a tumor suppressor, we searched TargetScan, miRbase, and MIRDB and ultimately identified FMR1 as a potential target of miR-323a-3p." (PMID 35351128, 2022). "Our previous results showed that FMR1 expression was up-regulated in CRC, and its expression level was significantly positively correlated with tumor size, degree of differentiation, TNM stage and metastasis in CRC patients." (PMID 36347844, 2022). "It appeared that IGF2BP1/3, ELAVL1, HNRNPA2B1, HNRNPC, KIAA1429, RBM15, LRPPRC, FMR1, YTHDF1/2 are highly expressed in the tumor while FTO, METTL14/16, WTAP, YTHDC1 and ZC3H13 are down-regulated." (PMID 35095993, 2021). "FXR1 mRNA levels along with two other FXR1 families of proteins FMR1 and FXR2 were determined in 521 tumor samples." (PMID 27606879, 2016). "Within such a context low FMR1 alleles not only may overcome embryo lethality (i.e., growth arrest) in human embryos but may also have a similar function in the induction of BRCA1/2-associated malignancies by overcoming the natural growth arrest functions of BRCA1/2 by inducing tumor growth." (PMID 22984553, 2012). "Thus, further exploration of the relationship between the regulation of FMR1 by FDX1 and the tumor immune microenvironment will contribute to a deeper understanding of tumor immunotherapy." (PMID 40118855, 2025). "The relationship between FMR1 expression and tumor immune infiltration was analyzed via the TISIDB database, and after co-culture, cytokine secretion by CD4+ T cells was assessed using ELISA following FMR1 knockdown in tumor cells." (PMID 41184982, 2025). "As expected, Ki67 and PDHA1 were expressed more strongly in the circRBM33-overexpressing tumour tissues than in the negative control tumours, while FMR1 was slightly altered." (PMID 37056926, 2023). "This study also demonstrated that FMR1 expression was positively correlated with activated CD4+ memory T cells and M1 macrophages, but negatively correlated with Tregs and monocytes, providing new insights into tumor immunotherapy for gastric cancer patients with high FMR1 expression." (PMID 41184982, 2025). "Strikingly, FMR1 mRNA expression was increased with a high statistical significance in the more aggressive TNBC subtype (i.e. ER/PgR and HER2 negative) compared to the ER/PgR and/or the HER2 positive tumours." (PMID 24092663, 2013).